MIRLET7A1HG (miRlet-7a-1/let-7f-1/let-7d cluster host gene)
Gene: Long non-coding RNA gene on chromosome 9 (94,166,258 to 94,200,905, forward strand). Ensembl gene ENSG00000269929.
Gene Ontology:
Biological process: miRNA-mediated post-transcriptional gene silencing
Cellular component: RISC complex